FASN (fatty acid synthase)
Diseases named in the same sentence as FASN in open-access papers (continued):
Sharing a sentence is not in itself a finding about the gene and the disease.
cancer (continued). "However, cancer cells can often use multiple ways to metabolically compensate or resist treatment; hence knockdown of FASN may improve the response to VPA in vivo." (PMID 39149696, 2024). "FASN, another vital enzyme that regulates lipogenesis, is extremely low in expression and activity in almost all normal adult tissues but is dramatically overexpressed or activated in many cancer types, catalyzing the synthesis of acetyl-CoA and malonyl-CoA into long-chain fatty acids." (PMID 38348027, 2024). "Mechanistically, loss of FASN resulting in ETC inhibition may similarly increase BCL-2/BCL-XL dependency, thereby lowering the threshold for inducing apoptosis, making cancer cells easier to target for cytotoxic signals from CATs, and accelerating CAT-mediated killing." (PMID 39349429, 2024). "The VCP/USP2/FASN axis could emerge as a compelling therapeutic target in cancer treatment." (PMID 39489738, 2024). "Furthermore, FASN appears to play a critical role in maintaining cancer stemness, suggesting it could be a vulnerability point of CSCs." (PMID 39332525, 2024). "In recent years, as the understanding of FASN's biological functions and pathological roles has deepened primarily in the context of cancer, it has been found that FASN is overexpressed in many types of cancer and is closely related to tumor cell growth, survival, and metabolic reprogramming." (PMID 39297226, 2024). "Loss of FASN results in a severe mitochondrial respiratory deficiency, characterized by a striking loss of ETC-OXPHOS complexes, which may account for the reduced carrying capacity (and increased susceptibility to T-cell cytolysis) of FASNKO cancer cells." (PMID 39349429, 2024). "In addition, TCA cycle intermediates can also be used for biosynthesis; and the SREBP1 transcription factor, an activator of lipid biosynthesis, or FASN fatty acid synthase, have been found to be upregulated in cancer cells with essential activities in tumorigenesis." (PMID 39195531, 2024). "Therefore, targeting FASN in cancer is becoming increasingly intriguing." (PMID 38933330, 2024). "Here, we aimed to clarify whether FASN is a metabolic driver of immune resistance in cancer cells." (PMID 39349429, 2024). "Furthermore, FASN may serve as an oncogenic factor owing to its role in regulating fatty acid synthesis and driving aberrant lipogenesis in cancer cells." (PMID 39489738, 2024). "Interestingly, we are beginning to accumulate evidence that FASN signaling may also mechanistically link cancer cell-intrinsic metabolic reprogramming to the cancer cell-extrinsic immune system." (PMID 39349429, 2024). "In addition, high expression of ROS in cancer cells may also induce apoptosis by inhibiting fatty acid synthase (FASN)." (PMID 37875983, 2023). "Together, the correlation between CSN6, FASN, and de novo lipid synthesis could be recapitulated in mouse xenograft cancer study, and tumor suppressive impact of orlistat in inhibiting FASN and lipid synthesis can be explored in hindering CSN6-overexpressing tumorigenicity." (PMID 37202390, 2023). "Thus FASN overexpression is frequently observed in many cancers." (PMID 37202390, 2023). "Our data suggest that FASN, which is important for catalyzing fatty acid synthesis in cancer, is functionally responding to the elevated levels of periostin in the tumor microenvironment, and that the increased expression of FASN in cancer cells may lead to increased fatty acid synthesis." (PMID 38049490, 2023). "Cancer-specific FBXW7β mutations that could not degrade FASN can lead to sustained lipogenesis in CRC." (PMID 37202390, 2023). "Thus, we showed that FASN, one of the key enzymes involved in cancer metastasis, had upregulated expression in CC cell lines and patient samples, indicating that FASN could be an essential oncogenic factor in CC pathology." (PMID 35597782, 2022). "In addition, FASN promotes cancer chemoresistance by regulation of apoptosis." (PMID 35646898, 2022).
cancer (continued). "Interestingly, FASN deficiency impaired glucose metabolism through downregulation of AKT and ERK signaling, significantly reducing ATP and lactate production, a finding that underlies the interconnection among different metabolic routes in cancer." (PMID 35159223, 2022). "We concluded that FASN may be an emerging target for reversing drug resistance in cancers." (PMID 36359776, 2022). "Therefore, in recent years, FASN has become a much-conceived drug target for cancer therapy." (PMID 36588702, 2022). "However, FASN inhibitors are used in other cancer types to guide HCC treatment." (PMID 36158697, 2022). "Therefore, we evaluated the correlation between FASN expression and immunity in pan-cancer." (PMID 36555243, 2022). "Moreover, FASN inhibition can decrease the cancer cell stemness in breast cancer and glioma." (PMID 35742944, 2022). "Therefore, we speculated that high FASN expression in the majority of cancers may enable tumor cells to evade the immune response by preventing the invasion of anti-tumor immune cells." (PMID 36555243, 2022). "Moreover, ACC or FASN inhibition partially blocks cancer growth in a subcutaneous NB model." (PMID 35764645, 2022). "Interestingly, catechin is a component of green tea, and as dietary manipulation is becoming an attractive strategy to enhance traditional cancer therapies, further research is warranted to fully elucidate the potential therapeutic effects of catechin as a FASN inhibitor." (PMID 34983949, 2022). "Therefore, we preliminarily determined that mir-195-5p might function by targeting FASN in different cancers." (PMID 36555243, 2022). "Components of altered metabolic lipid pathways that could function as potential prognostic biomarkers or therapeutic targets to prevent the growth of cancer cells or to overcome chemotherapy resistance include cholesterol, fatty acid synthase, autotaxin ceramide, and CERT." (PMID 35634242, 2022). "Furthermore, it has been shown that HTyr exerted its anti-proliferative and pro-apoptotic effects in human HCC cells by inhibiting the expression of fatty acid synthase (FAS) and farnesyl diphosphate synthase (FPPS), whose higher expression was associated with higher aggressiveness of this cancer." (PMID 33513799, 2021). "However, whether FASN can play a role in the tumorigenesis of cancers through these mechanisms remains unclear." (PMID 34879004, 2021). "However, the effect of USP14 on the function or stability of FASN in cancer cells is completely unknown." (PMID 34948233, 2021). "Additionally, several features (e.g., gene expression, survival prognosis, genetic alteration, DNA methylation, protein phosphorylation, immune cells, or relevant cellular pathways) were gathered to evaluate the regulatory mechanism of FASN in the tumorigenesis of cancers." (PMID 34879004, 2021). "In addition, USP14 overexpression reduced the FASN protein level in cancer cells." (PMID 34948233, 2021). "Therefore, we can speculate that combination of statins and SREBP/FASN inhibition might be an efficient strategy to induce ferroptosis in this cancer type." (PMID 34485382, 2021). "Additionally, O. japonica inhibited tumor-specific metabolism in proliferating cancer cells by suppressing the expression of α-enolase, phosphoglycerate dehydrogenase (a regulator of the serine synthesis pathway), and fatty acid synthase, resulting in lower biosynthesis demands from cancers." (PMID 33567572, 2021). "Inhibition of FASN could suppress the proliferation, invasion, and metastasis of cancer cells." (PMID 34123778, 2021). "Most FASN inhibitors have unexpected toxicities in vivo that may be attributed to a lack of target selectivity, pharmacological side effects, and metabolic flexibility of cancer cells." (PMID 34948233, 2021).
cancer (continued). "Moreover, the impaired response of cancer cells to DTIC in an obese mouse model was accompanied by the elevated expression of fatty acid synthase, Cav-1, and P-glycoprotein (P-gp), which is a multidrug resistance protein associated with pumping out drugs from targeted cells." (PMID 33430277, 2021). "Fatty acid synthase, which is highly expressed in most human carcinomas, is a key lipogenic enzyme that catalyzes the terminal steps in the de novo biogenesis of fatty acids in cancer pathogenesis 130 and plays critical roles in cancer proliferation and metastasis." (PMID 33613101, 2021). "However, the demands of phGCs and hGCs for FASN are obviously lower than those of cancer cells, so the sensitivity of GCs to FASN inhibition may also be lower than that of cancer cells." (PMID 32676035, 2020). "Some studies have pointed out that FASN inhibitors could also induce the cell cycle arrest at S/G2/M and apoptosis of cancer cells, but only caused cell cycle deceleration without apoptosis for normal cells." (PMID 33194756, 2020). "This means that FASN may be involved in chemoresistance of cancer cells." (PMID 33194756, 2020). "It has also been proposed that, instead of energy storage in the form of triacylglycerol, newly synthesized lipids produced by FASN in cancer cells preferentially became phospholipids, which were involved in cell signaling or cell membrane composition that might contribute to resistance." (PMID 32944403, 2020). "Therefore, FASN is a potential molecular target for cancer treatment." (PMID 32699531, 2020). "Therefore, FASN may be a promising therapeutic target used to reduce cancer progression and improve prognoses, and it is crucial to investigate the FASN protein interaction network in order to elucidate the molecular pathogenesis that drives cancer." (PMID 32699531, 2020). "Therefore, FASN inhibitors seem to play promising role in cancer treatment." (PMID 32826925, 2020). "In addition, FASN suppression might also cooperate in radio-sensitization and with antiangiogenic agents, by triggering strong tumor hypoxia because cancer cells escape antiangiogenic-driven hypoxia by upregulation of FASN-related lipogenesis." (PMID 31921669, 2019). "Therefore, the discovery of novel FASN inhibitors will be highly expected to treat cancers." (PMID 30824767, 2019). "Furthermore, cancer cells are also efficient in taking up fatty acids from the microenvironment, another reason FASN inhibition alone may only target a small subset of cells and combination therapies would be necessary." (PMID 35582564, 2019). "Here, we identified that OvCa cancer-intrinsic FASN might initiate this process." (PMID 30619288, 2018). "Indeed, it has been demonstrated that silencing of SREBP-1 caused a decrease in SREBP-1 downstream lipogenic genes, including FASN, inhibition of cell growth and aggressive behaviors, and induction of programmed death in PCa, endometrial, and ovarian cancer cells." (PMID 30301150, 2018). "Therefore, it will be interesting to explore whether USP14 could regulate FASN protein stability in cancer cells to promote tumorigenesis." (PMID 30425250, 2018). "However, cancer cells still have higher levels of FASN than those of lipogeneic tissues." (PMID 29588626, 2018). "Further, FASN and de novo FA biosynthesis may regulate other cancer-related signaling networks." (PMID 28654693, 2017). "Thus, FASN has become an attractive target for cancer therapy in last 15 years." (PMID 27270654, 2016). "Indeed, fatty acid synthase is a potential therapeutic target in cancer." (PMID 27213347, 2016). "The discovery of FASN signaling as a hitherto unrecognized organizer of breast tissue architecture can provide new therapeutic avenues aimed to chronically restrain the life-threatening potential of invasive carcinomas by using FASN-based differentiation therapies." (PMID 27223424, 2016). "Inhibition of FASN expression could repress cell proliferation in various cancers." (PMID 25433947, 2015).
cancer (continued). "Interestingly, inhibition of SREBP1 or its downstream target FASN sensitizes cancer cells to death ligands, a finding that may open new therapeutic approaches." (PMID 24158494, 2014). "We postulate that inhibition of FASN impairs the production of fatty acid levels responsible for membrane formation, intracellular signaling pathways, and protein modification at post-translational process as well as storage of energy in cancer cell proliferation process." (PMID 25255125, 2014). "Thus, we propose to continue the open perspective hypothesis that capsaicin can become one of the FASN inhibitors that will find an ultimate clinical application in treating cancer patients." (PMID 25255125, 2014). "Therefore, targeting FASN has come to the attention of many in the drug industry due to the discovery that the inhibition of de novo synthesis of fatty acid can be used to treat cancer patients." (PMID 24778702, 2014). "Thus, it affirms that FASN would be a potential target for anti-cancer therapy of capsaicin." (PMID 25255125, 2014). "Most significantly, our results show that VPS4B downregulation decreased the expression of FASN by simultaneously decreasing its rates of synthesis and increasing the rate of its degradation, suggesting that both de novo fatty acid synthesis and fatty acid β-oxidation are tightly coupled in cancer." (PMID 23431444, 2013). "Importantly, we and others have demonstrated that inhibition of FASN with pharmacological inhibitors is selectively cytotoxic to human cancer cells and leads to a significant antitumor effect, suggesting that activation of fatty acid synthesis is required for carcinogenesis." (PMID 23725225, 2013). "Recent studies revealed that FASN may contribute to cancer cell metastasis." (PMID 23599729, 2013). "Whether FASN is regulated post-transcriptionally in cancer cells remains unclear." (PMID 21080941, 2010). "Because of their pro-oncogenic activities, defining the respective domains of FASN and OGT that drive their interaction is of special interest so as to be able to propose novel therapeutic avenues for cancer treatment, especially hepatocarcinomas." (PMID 41550490, 2026). "As is the case with FASN, OGT is highly expressed in a large variety of cancers where it contributes to the processes of carcinogenesis." (PMID 41550490, 2026). "Linolenic acid has also been shown to inhibit the PI3K/Akt signaling pathway and suppress fatty acid synthase (FASN), an enzyme overexpressed in many cancers." (PMID 40420175, 2025). "Targeting FA synthesis by inhibiting FASN, ACLY, and ACSS2 has been the subject of numerous preclinical and several clinical studies in various cancers, including breast, lung, colon, prostate, and bladder." (PMID 40723225, 2025). "Among lipogenic enzymes, ATP citrate lyase (ACLY), the rate-limiting enzymes acetyl-CoA carboxylase (ACC) and fatty acid synthase (FAS), are the most expressed enzymes in many cancer types." (PMID 39886047, 2025). "Key enzymes involved in this process, such as ATP-citrate lyase, acetyl-CoA carboxylase, and the multifunctional fatty acid synthase (FASN), are regulated by the transcription factor REBP1 and the mTOR signaling pathway in cancer cells." (PMID 40548063, 2025). "The overexpression of critical enzymes, such as FASN and ACLY, enables cancer cells to enhance de novo fatty acid synthesis, thereby driving their proliferation and survival." (PMID 41009695, 2025). "Our previous research also demonstrated the protective effects of diallyl sulfide (DAS) in BaP-induced lung carcinogenesis and its role in modulating fatty acid synthase (FASN), a critical factor in cancer metabolism." (PMID 40284009, 2025). "Consistent with this assumption, cancer cells often show upregulation of genes involved in fatty acid synthesis, such as SREBP-1, ACC1, fatty acid synthase (FASN), and ATP citrate lyase (ACLY)." (PMID 40563460, 2025).
cancer (continued). "FASN and SCD1 are two pivotal enzymes in lipid metabolism that have gained significant attention as potential targets for cancer therapy." (PMID 40469185, 2025). "In cancer cells, FASN overexpression promotes their survival and proliferation via the activation of HER1/2 and EGFR receptors, which in turn induce FASN expression via the activation of the MAPK and PI3K/Akt/mTOR pathways." (PMID 40723225, 2025). "FASN contributes to constructing new cell membranes and providing energy to tumor cells by promoting FAS, making it a potential target in cancer therapy." (PMID 40696413, 2025). "Several enzymes involved in de novo fatty acid synthesis, including FASN, ACLY, SCD, and ACSS2, are abnormally expressed in various cancers, promoting fatty acid synthesis and contributing to malignant tumor phenotypes." (PMID 41285764, 2025). "Fatty acid synthase (FASN) is the key enzyme in fatty acid synthesis, and in recent decades the role it plays in tumor initiation, growth, cancer cell survival, metastasis, and therapeutic resistance has been reported." (PMID 40565145, 2025). "Like FASN, OGT is overexpressed in cancers, including HCC, and is thought to participate in many hallmarks of cancer by regulating protein expression, activity, subcellular location, and interactions." (PMID 40684943, 2025). "Further studies have proven that, in cancer cells, the PI3K/AKT signaling pathway promotes the expression of ATP citrate lyase (ACL), ACC, and FASN by upregulating SREBP-1." (PMID 40432434, 2025). "At the metabolic level, UA intervenes in lipid metabolism by inhibiting fatty acid synthase (FASN) and acetyl-CoA carboxylase (ACC), thereby reducing the supply of lipids required for cancer cell proliferation." (PMID 40760406, 2025). "FASN knockdown lessens PARP-1 expression and NHEJ repair regulation, thus suggesting that FASN has a role in maintaining the genome integrity against cancer cells." (PMID 40869407, 2025). "Unlike normal cells, which primarily obtain fatty acids (FAs) from dietary sources, cancer cells enhance de novo fatty acid synthesis by modulating ACLY, ACC, FASN and SCD." (PMID 41154605, 2025). "Mechanistically, FASN, which is upregulated in CRC tissues, drives cancer cell proliferation, metastasis, and PC metabolism through the SP1/PLA2G4B axis, subsequently suppressing the antitumor response of natural killer (NK) cells in a PC-dependent manner." (PMID 40148316, 2025). "Many key enzymes of lipid synthesis and metabolic processes, such as ACLY, FASN, and SCD1, are highly expressed in cancers, promoting cell proliferation while enhancing cell stemness." (PMID 40002387, 2025). "Fatty acid synthase (FASN) inhibitors have been shown to impair MDSC function and survival in various cancer models." (PMID 40051496, 2025). "For instance, the expression of specific enzymes involved in fatty acid metabolism, such as fatty acid synthase (FASN), has been shown to correlate with NF-κB activity and cancer aggressiveness." (PMID 40542303, 2025). "Critical enzymes in the lipid metabolism pathway, such as acetyl coenzyme A carboxylase 1 (ACC1), fatty acid synthase (FASN), ATP citrate lyase (ACLY), and carnitine palmitoyltransferase 1 (CPT1A), are upregulated across a broad spectrum of cancers." (PMID 41145471, 2025). "Elevated expression of both FASN and FAK protects cancer cells from apoptosis, enhancing their survival." (PMID 40733158, 2025). "Fatty acids are not only synthesized intracellularly by FASN but also taken up from the extracellular environment through CD36, a fatty acid translocase that has emerged as a therapeutic target in cancer." (PMID 40552664, 2025). "A review of the literature on PC metabolism in various cancers revealed that FADS1, FASN, PCYT1A, LPCAT1, and PLD2 are involved in PC metabolism in multiple cancers." (PMID 40148316, 2025).